MTOR (mechanistic target of rapamycin kinase)
Diseases named in the same sentence as MTOR in open-access papers (continued):
Sharing a sentence is not in itself a finding about the gene and the disease.
tumor (continued). "For example, miR-100 suppresses tumors by targeting mTOR but is downregulated in CS, while miR-30a inhibits tumor growth by targeting SOX4." (PMID 39590345, 2024). "Trials exploring combinations of the MAPK pathway and PI3K/mTOR pathway have proven unsuccessful due to their low efficacy because of low tumour penetrance and high toxicity." (PMID 39272879, 2024). "JNK and yorkie (yki) mediate their upregulation through the activation of the nutrient sensor mTOR and phosphorylation of ribosomal protein S6 (RpS6) to promote tumour growth and invasion." (PMID 39682725, 2024). "Akt’s modulation of these factors leads to the inhibition of tumor suppressor gene expression and the phosphorylation of critical enzymes and regulators such as glycogen synthase kinase-3 and the mammalian target of rapamycin (mTOR)." (PMID 38473413, 2024). "SCD1 overexpression inhibited lipid peroxidation, affected mTOR pathway and eventually inhibited autophagy, largely considered as tumor suppressive mechanism through cell cycle arrest and maintenance of genome and organelle integrity." (PMID 38406265, 2024). "In this regard, inhibiting CD109 is known to reduce EGFR signaling, suppress the Akt/mTOR pathway, and increase tumor cell sensitivity to EGFR inhibitors, highlighting its potential as a promising therapeutic target in lung cancer." (PMID 39990858, 2024). "The mTOR inhibitor everolimus impedes glucose uptake and tumor angiogenesis by downregulating HIF-1α expression." (PMID 39610917, 2024). "The stimulation of the mammalian target of rapamycin (mTOR) pathway has been observed in this particular tumour." (PMID 38765391, 2024). "It has been demonstrated in earlier research that PTEN functions as a tumor suppressor by negatively modulating the PI3K/Akt/mTOR signaling pathway." (PMID 38365726, 2024). "KEGG pathway enrichment analysis of the phagocytotic resistance genes identified from tumor cells were mainly enriched in metabolic pathways, cell junctions, and major tumor signaling pathways such as Wnt, mTOR, AMPK, and PI3K-AKT signaling pathways." (PMID 38773982, 2024). "The overexpression of the tumor suppressor lncRNA GAS5 inhibits GC development through percolating miR-106a-5p through the Akt/mTOR pathway." (PMID 39125625, 2024). "TVB-3166 and TVB-3664 promote tumor cell apoptosis and inhibit tumor progression via the PI3K-Akt-mTOR pathway and β-catenin signal transduction." (PMID 38302980, 2024). "Proteins were then extracted from frozen tumor specimens to evaluate the expression mTOR and phospho‐mTOR in each sample." (PMID 38250695, 2024). "We also observed a dose-dependent inhibition of LM-tumor growth and NF-κB, mTOR, p70S6K1, and 4E-BP1 signaling while inducing Nrf2/HO1 pathway induction LM tumors collected from hens fed with curcumin (p < 0.05)." (PMID 39770574, 2024). "MiR-383-5p has a role as a tumor suppressor through an inhibitory effect on the PI3K/AKT/mTOR pathway and inhibiting tumor PD-L1 expression." (PMID 38462658, 2024). "The functional relevance of these pathways is supported by increased expression in alternative pathways such as PI3K-AKT and mTOR after tumor dedifferentiation and BRAF inhibitor treatment." (PMID 38275291, 2024). "The PI3K/Akt/mTOR pathway acts as a critical player in tumor cell proliferation, vascular growth as well as metastasis." (PMID 38526702, 2024). "In a mouse model, tumor cells also induce mTOR expression in microglia, and mTOR-mediated STAT3 signaling contributes to the M2-like microglial phenotype, which impairs effector T cell infiltration, tumor proliferation, and immune responses." (PMID 39194524, 2024). "MTOR signaling plays an important role in apoptosis, autophagy, and tumor metabolism and, as such, is highly interconnected to other pathways identified here, such as PI3K-Akt, MAPK, or AMPK signaling." (PMID 39766892, 2024).
tumor (continued). "In summary, we employed WGCNA to identify gene modules corresponding to the NOR-CIN-CC transition and discovered that CARMN functions as a hub gene and tumor suppressor in CC by modulating both ROS/Akt/mTOR and MAPK13-mediated MAPK signaling pathways." (PMID 39558374, 2024). "The last part of selected genes are strictly related PI3K/AKT/mTOR pathway, which is a critical regulator of tumor development, progression, and resistance to therapy." (PMID 39850811, 2024). "The PI3K/AKT/mTOR pathway is a critical signaling pathway involved in tumor growth, proliferation, and survival; its activation can promote resistance to ET." (PMID 38930141, 2024). "The lin-35 strain present in the current study is the orthologue of pRb in mammals and has a tumours suppressor effect by inhibiting mTOR signalling." (PMID 39558974, 2024). "In anti-tumor T-cell responses, large amounts of K+ produced by necrotizing tumor cells lead to a functional decline in CD8+ T cells owing to increased intracellular K+ affecting the Akt-mTOR pathway." (PMID 38915413, 2024). "SLC7A5 knockdown reduced mTOR pathway activity and suppressed the proliferation and metastasis of tumor cells." (PMID 39698464, 2024). "Studies have shown that TIM-3, through binding to its ligand phosphatidylserine (PtdSer), induces inhibition of downstream signaling pathways such as PI3K/mTOR, which in turn leads to dysregulation of NK cells and tumor evasion of the immune." (PMID 39906665, 2024). "On the other hand, mTOR expression level showed a 1.8-fold increase in tumor tissue treated with Mo/Caf/CsNPs when compared to the positive control group." (PMID 39103402, 2024). "mTOR has been reported to restrain the tumor suppressor function of 4E-BP1 by phosphorylation, which can be reactivated in response to mTOR inhibition." (PMID 38992135, 2024). "Glutamine can also suppress tumor growth by inhibiting cell autophagy through mTOR pathway activation and ROS elimination." (PMID 38510646, 2024). "It was demonstrated that triggering the mTOR cascade increases tumor development via controlling angiogenesis, lipid metabolism, glycolysis, growth factor receptor pathway, and autophagy." (PMID 39519654, 2024). "Incomplete protein synthesis is one of the triggers of the ER stress induction in cells, with different mTOR inhibitors being able to activate the PERK signaling in tumor cells." (PMID 38418814, 2024). "PI3K/AKT/mTOR signaling has an indispensable regulatory effect on tumor growth, migration, survival, and angiogenesis." (PMID 38555280, 2024). "A large number of studies have confirmed that the PI3K/Akt/mTOR signaling pathway can accelerate the activity of tumor cells and regulate the receptors to promote the proliferation and metastasis of tumor cells." (PMID 38544826, 2024). "They benefit from such neoadjuvant therapy based on the use of mTOR inhibitors because it reduces the size of the tumor, thus facilitating surgery and reducing the number of postoperative complications." (PMID 39410026, 2024). "Our research involved a thorough analysis of the PI3K/mTOR pathway, which plays a crucial role in the survival of tumor cells, resistance to apoptosis, and angiogenesis." (PMID 38461536, 2024). "Risk score was significantly positively correlated with most of the tumor-related signaling pathways, such as MTOR, Insulin, ERBB and Wnt signal pathways, while significantly negatively related to PPAR and Notch signaling pathways." (PMID 38685045, 2024). "Everolimus is an mTOR inhibitor, disrupt tumor proliferation under overexpression of RB1CC1, which is a recently identified tumor suppressor implicated in autophagic and apoptosis." (PMID 38443363, 2024).
tumor (continued). "Everolimus (EVE), the only approved oral mTOR inhibitor can effectively suppress tumor cell proliferation, ameliorate cellular oxidative stress, and show anti-angiogenic properties." (PMID 39736867, 2024). "The activation of mTOR can inhibit autophagy and promote cell proliferation, and the PI3K/AKT/mTOR signal pathway contributes to angiogenesis in the tumor microenvironment." (PMID 38800967, 2024). "BEZ235 (Dactolisib): Dual PI3K/mTOR inhibitor, reduces tumor cell proliferation and induces apoptosis." (PMID 39156976, 2024). "VO-OHpic, an inhibitor of PTEN, relieves the inhibition of the mTOR signaling pathway, weakens lipid metabolism, and effectively promotes the activation of anti-tumor immunity after chemotherapy." (PMID 38644503, 2024). "In a sufficient supply of nutrients and energy, activated AKT will phosphorylate mTOR, further promoting tumor cell growth." (PMID 38339127, 2024). "mTOR inhibitors, such as rapamycin and everolimus, exhibit clear effectiveness in treating different tumor types in TSC." (PMID 40217423, 2024). "Although targeted therapies that inhibit angiogenesis and mTOR pathways can lead to initial tumor control, most patients develop resistance." (PMID 39272694, 2024). "Our findings align with these observations, demonstrating that MTOR plays a central role in enabling metabolic adaptations that support rapid tumor growth." (PMID 39742278, 2024). "The Akt/mTOR pathway, crucial in tumor cell proliferation, metabolism, and survival, exhibits a dual role: its inactivation suppresses tumor growth but also triggers autophagy." (PMID 38664366, 2024). "Abnormal activation of the PI3K/AKT/mTOR signaling pathway plays an important role in tumor cell proliferation, survival, angiogenesis, invasion and migration." (PMID 38263056, 2024). "Although rapalogs are generally used to reduce the risk of tumours after transplantation, there is a new study from 2022 questioning the effectiveness of early conversion to mTOR inhibitor-based IS regimens in reducing tumour incidence." (PMID 38341510, 2024). "This downregulation of mTOR expression is crucial in inhibiting the PI3K/AKT/mTOR pathway, which is known to play a significant role in cell proliferation and tumour growth." (PMID 39263322, 2024). "The western blot was utilized to determine the protein expression level of NSUN4 and mammalian target of rapamycin (mTOR) pathway-related proteins in cells and mouse tumor tissues." (PMID 39634439, 2024). "Inhibit the proliferation of tumor cells and induce apoptosis; the levels of p-Akt, p-mTOR, p-MEK1/2, p-ERK1/2, Bcl-2 and Bcl-xL are down-regulated, and the level of cleaved-Caspase 3 is up-regulated." (PMID 39045282, 2024). "When activated, PI3K/Akt leads to the inhibition of pro-apoptotic factors, and stimulates mTOR (mammalian target of rapamycin), promoting cell growth and protein synthesis—processes essential for tumor development and metastatic potential in CRC." (PMID 39839775, 2024). "For this purpose, we initially induced autophagy by treating tumor cells with rapamycin, the well-known autophagy inducer that acts by inhibiting mTOR kinase activity, at a concentration of 100 nM for 2 h." (PMID 39201776, 2024). "Excessive production of the mTOR serine/threonine kinasecan lead to microglia attraction, tumor formation, and primary T cells death within the tumor microenvironment." (PMID 38243240, 2024). "Numerous previous studies have reported the mTOR signaling pathway as a key factor in tumor cell metabolism regulation." (PMID 39048994, 2024). "By focusing on AKT/mTOR signaling, induced expression of miR-147 decreased tumor growth and metastasis." (PMID 38812786, 2024). "Tumor-associated macrophages, which are immunosuppressive cells in tumor-bearing hosts, have also been demonstrated to exhibit pro-tumoral activity via mTOR signaling activation." (PMID 38791040, 2024).
tumor (continued). "The investigators reported that ETV7 belonged to a rapamycin-insensitive mechanistic target of rapamycin kinase (mTOR) complex, which promoted tumor onset and accelerates tumor penetrance." (PMID 38200280, 2024). "In summary, our findings unveil a signaling network involving METTL3/FGF2/PI3K/AKT/mTOR in LUAD and shed light on the molecular mechanism underlying tumor malignant progression while holding great significance for targeted therapy in research on LUAD." (PMID 39497721, 2024). "These small-molecule inhibitors specifically block the activity of PI3K, Akt, or mTOR, disrupt downstream signaling cascades, and inhibit tumor growth." (PMID 38172946, 2024). "Compounds like Rapamycin, which activates autophagy by inhibiting the mTOR complex, reduces cell proliferation and, thus, tumor progression in vivo." (PMID 39289189, 2024). "For example, the loss of the 3p chromosome arm disrupts critical genes like VHL, PBRM-1, BRCA1, and MTOR that act as tumor suppressors." (PMID 39796121, 2024). "Insulin was suggested to promote tumor progression through INSR‐A with activation of AKT/mTOR signaling." (PMID 38952575, 2024). "In cancer, dysregulations in mTOR pathway are leading to uncontrolled cell growth and tumor progression." (PMID 39138146, 2024). "Upregulation of β2-AR by HER2 can activate the PI3K/AKT/mTOR pathway, leading to tumor resistance to trastuzumab, a first-line treatment for both GC and BC." (PMID 38081962, 2024). "At the same time, PI3K/AKT/MTOR signaling was also down-regulated, confirming the effects of Alpelisib on tumor cells." (PMID 38310289, 2024). "Our preliminary data demonstrated that LAT1 is highly expressed and closely correlated with hypoxia, mTOR pathway, and tumor progression." (PMID 39290273, 2024). "By downregulating mTORC1 and its pathway, mTOR inhibitors prevent excessive anabolism and energy utilization in tumor cells." (PMID 39339165, 2024). "They revealed that the PD-L1 of tumor cells promoted mTOR signaling which inhibited autophagic flux and thus maintained the expression of PD-L1 protein upregulated in tumor cells." (PMID 38600305, 2024). "The Akt/mTOR signaling pathway is an important regulatory signaling pathway for tumor proliferation and invasion." (PMID 39107297, 2024). "This combination inhibits PI3K-mediated activation of mTOR and downstream effectors, thereby synergizing tumor cells." (PMID 38172946, 2024). "Studies show Rapamycin to 50% inhibit mTOR signaling in EBV-associated nasopharyngeal cancer, resulting in a 45% decrease in tumor size." (PMID 39772235, 2024). "mTOR facilitates tumorigenesis and progression by orchestrating tumor cell proliferation, angiogenesis, as well as the upregulation of genes associated with chemotherapy and immune evasion." (PMID 39220130, 2024). "The activation of the mTOR pathway has been shown to enhance tumor growth by regulating glycolysis, angiogenesis, growth factor receptor pathways, lipid metabolism, and autophagy." (PMID 39201363, 2024). "It was reported that Met activates AMP‐activated protein kinase (AMPK), and inhibit mammalian target of rapamycin (mTOR) pathway, which is crucial for tumor cell growth and proliferation." (PMID 39606802, 2024). "Targeted therapy with mTOR inhibitors is a strategy to prevent further tumor progression and promote regression of existing tumors." (PMID 39202574, 2024). "The main mechanism of Bio-nFeR action consists of promoting tumor dormancy through a combined induction of antiproliferative signals and inhibition of the mTOR pathway." (PMID 39497135, 2024). "mTORC2 is composed of mTOR, Rictor, Sin1, and mLST8, which play a role in cell growth and proliferation and cytoskeletal remodeling, and mTORC2 promotes tumor development by controlling cell proliferation and survival." (PMID 39796003, 2024). "SIRT4, in contrast, exerts tumor-suppressive effects by inhibiting aerobic glycolysis and attenuating the proliferative signals in the mTOR pathway." (PMID 39682281, 2024).
tumor (continued). "mTOR activation allows for elevated levels of proteins, nucleotides, and lipids, making the protein kinase imperative in sustaining tumor growth." (PMID 39199674, 2024). "The mTOR signaling pathway is critical in tumor progression through proliferation, migration, angiogenesis, glycolytic metabolism, and lipid metabolism." (PMID 38791040, 2024). "Wnt7b is upregulated in OS cell lines and assists in tumor cell proliferation, possibly by activating mTOR C1 via PI3K/Akt." (PMID 39119480, 2024). "Downstream, mTOR regulates protein synthesis and cellular metabolism, contributing to tumor growth and progression." (PMID 39349425, 2024). "The phosphoinositide 3-kinases (PI3K) and their downstream mediators Akt and mTOR constitute the PI3K/Akt/mTOR signaling cascade, which regulates abnormal cell proliferation and differentiation and promotes tumor cell growth." (PMID 38541744, 2024). "Increased ALDH-1 expression is associated with tumor cell aggressiveness and has been linked to increased activity in PI3K/Akt/mTOR signaling in breast cancer." (PMID 39107323, 2024). "On the other hand, PI3K/AKT/mTOR inhibitors can improve tumor immunosurveillance efficacy by downregulating the immunosuppressive pathways and activating antitumor immune responses in the TME." (PMID 37046703, 2023). "Previous studies have shown that the PI3Kγ signaling pathway of TAMs inhibits the activation of NF-κB through Akt and mTOR, which mediates immunosuppression to promote tumor growth." (PMID 37834375, 2023). "Two of the five clusters were highly similar, with lower myogenesis and signature high mechanistic target of rapamycin (mTOR) expression, but expression of glycolysis-related genes, as well as the location in the tumor differed between them." (PMID 36672284, 2023). "FBXW7 targets mTOR and mediates mTOR degradation in the tumor through direct physical combination with mTOR." (PMID 36998461, 2023). "mTOR also increases tumor angiogenesis and controls the production of hypoxia-inducible proteins, both of which are significant in KIRC." (PMID 37383233, 2023). "The PI3K/AKT/mTOR is suggested to act as an essential part in the tumor's development and its potential as new therapeutic target." (PMID 36653904, 2023). "CD98hc boosts cancer cell proliferation and tumor growth by transporting amino acids, augmenting the integrin signaling, and activation of the mTOR, PI3K/AKT and MAPK signaling pathways." (PMID 37823053, 2023). "As one of the classical tumors signaling pathways, PI3K/AKT/mTOR has been shown to regulate both asis and autophagy to exert anti-tumor effects." (PMID 36864518, 2023). "Meanwhile, inhibiting both PI3K and mammalian rapamycin receptor (mTOR) can simultaneously improve the efficiency of anti-tumor therapy." (PMID 36986560, 2023). "Altogether, these findings suggest that pharmacological VC regulates cell size, cell proliferation, autophagy, apoptosis, and tumor activity by inhibiting the activation of the mTOR pathway." (PMID 36787291, 2023). "Our data offer valuable insights into the tumor secreted protein, IFI35, which enhances the proliferation and cytotoxicity of CD8+ T cells by activating the PI3K/AKT/mTOR signaling pathway and suppresses tumor growth in a CD8+ T cell-dependent manner." (PMID 37380972, 2023). "Rapamycin is an inhibitor of the mTOR pathway which inhibits several processes involved in tumor cell proliferation and survival." (PMID 37444627, 2023). "Everolimus inhibits tumor growth not only through affecting the PI3K/Akt/mTOR pathway but also through blocking tumor angiogenesis via downregulating the expression of HIF-1 and VEGFs." (PMID 36908706, 2023). "The PI3k/Akt/mTOR-glycolysis-NO feedback loop is activated by PcrV, which encourages TAMs repolarization and cytotoxicity against tumor." (PMID 37828561, 2023). "Gedatolisib can inhibit the activation of the PI3K/mTOR signalling pathway and induce G0/G1 cell cycle arrest, which has great potential for tumour therapy." (PMID 37489050, 2023).